TMPRSS2 (transmembrane serine protease 2)
Diseases named in the same sentence as TMPRSS2 in open-access papers (continued):
Sharing a sentence is not in itself a finding about the gene and the disease.
COVID-19 (continued). "Both TMPRSS2 and ACE2 are expressed in lung tissues, as implicated in the clinical manifestations of COVID-19." (PMID 35017320, 2022). "Both ACE2 and TMPRSS2 are expressed in host cells, particularly the alveolar epithelial type II cells of COVID-19 patients." (PMID 35619076, 2022). "Exemplifying this, amongst the most promising targets for early severe COVID-19 predicted by our model were Camostat and Apilimod, primarily targeting TMPRSS2 and PIKfyve respectively." (PMID 35165389, 2022). "Different immune responses, the RAAS system, ACE2, and TMPRSS2 role, and hormonal status are biological sex-related differences that count markedly towards the different COVID-19 progression among the sexes." (PMID 35629311, 2022). "In sum, TMPRSS2 represents an attractive drug target in COVID-19, and downregulation of its enzymatic activity with active and selective inhibitors should significantly improve health rehabilitation." (PMID 35804152, 2022). "We also found that TMPRSS2 and CXCL10 proteins are interconnected along with other protein components associated with COVID-19 development." (PMID 36239108, 2022). "Among different genes potentially involved in COVID-19, the association between the polymorphisms of renin-angiotensin-aldosterone system-related genes, i.e., ACE2 and TMPRSS2 and the severity of COVID-19 disease have been the most investigated." (PMID 36360172, 2022). "In this work, we detected the clinical significance of IFNAR2 (2 SNPs), SLC6A20 (1 SNP) with respect to COVID-19 susceptibility and ADAM17 (2 SNPs), TMPRSS2 (1 SNP), TYK2 (1 SNP), DPP9 (1 SNP) with respect to the severity of the disease." (PMID 36292769, 2022). "TQ, a major component of N. Sativa, has been reported to potentially suppress the development of COVID-19 by binding to TMPRSS2." (PMID 36558177, 2022). "AAT acts as an inhibitor of inflammatory molecules (e.g., IL-8, TNF-α) and of proteases involved in the pathophysiology of COVID-19 (e.g., elastase, TMPRSS2 and ADAM17)." (PMID 35163482, 2022). "Several previous studies have reported potential serine protease inhibitors of TMPRSS2 for COVID-19 treatment." (PMID 35207518, 2022). "The main objective of the present study is to elucidate effects of naturally occurring variants within ACE1, ACE2, TMPRSS2, IFITM3 and VDR genes on clinical severity of COVID-19 and/or the outcome of SARS-CoV-2 infection." (PMID 35949487, 2022). "We then review the different classes of TMPRSS2 inhibitors and their clinical development, with a focus on COVID-19 treatment." (PMID 35163273, 2022). "In this study, we identified 1,656 genes co-expressed with CXCL10 in both PRAD and COVID-19 and 2,669 genes co-expressed with TMPRSS2 for the same." (PMID 36239108, 2022). "Accordingly, selective inhibitors of TMPRSS2 represent potential tools for prevention and treatment of COVID-19." (PMID 36081512, 2022). "ACE2 and TMPRSS2 are the two major host receptors which contribute to the virulence and the severe pathogenesis of COVID-19." (PMID 36589459, 2022). "The pathogenesis of COVID-19 occurs when the virus enters a host respiratory epithelial cell using an S protein primed by transmembrane serine protease 2 (TMPRSS2) binding with a host membrane receptor, such as angiotensin-converting enzyme 2 (ACE2) receptor." (PMID 35625619, 2022). "Concerning COVID-19 susceptibility, the most studied polymorphisms are located in the ACE2 and TMPRSS2 genes, which are involved in viral binding and entry into host cells." (PMID 36672770, 2022). "PRAD is a prevalent cancer type in males, and multiple biomolecules that act as markers of PRAD are in common with COVID-19 (Both TMPRSS2 and CXCL10 were upregulated in PRAD patients)." (PMID 36239108, 2022). "The infection route of COVID-19 involves introduction and infection in vivo when transmembrane protease, serine 2 (TMPRSS2) is cleaved after the spike protein of the COVID-19 virus binds to the angiotensin-converting enzyme 2 receptor." (PMID 35745792, 2022).
COVID-19 (continued). "We further analyzed TMPRSS2 expression using a dataset containing COVID-19-infected lungs and control lungs, and we found that the levels of TMPRSS2 in COVID-19-infected lungs were significantly reduced compared to the control lungs." (PMID 36364238, 2022). "Studies have shown that the highest expression of ACE with TMPRSS2 is detected in nasal secretory cells, which correlates with COVID-19 pathology." (PMID 35743381, 2022). "The tested peptidomimetics are stable in human plasma and serum for at least 10 days, suggesting that these TMPRSS2 inhibitors are promising leads for further development as antiviral drugs in COVID-19 therapy and other viral diseases." (PMID 35804152, 2022). "TMPRSS2 was found to favor the immune escape of COVID-19, and TMPRSS4 was upregulated in malignancies of the stomach, liver, and prostate." (PMID 36046240, 2022). "Based on our in silico analysis, it can be said that TMPRSS2 and CXCL10 can serve as biomarkers for analyzing the susceptibility of prostate cancer patients towards COVID-19." (PMID 36239108, 2022). "Accordingly, a drug that inhibits TMPRSS2 activity is highly likely to be an effective therapeutic drug for COVID-19." (PMID 35745792, 2022). "In conclusion, polymorphisms in the ApoE, ACE1, TMPRSS2, CCR5, and HLA loci appear to be involved in the susceptibility to and/or severity of COVID-19." (PMID 35793369, 2022). "The aim of this study was to investigate the association between these four COVID-19 associated SNPs (ACE2 rs2285666, ACE2 rs2074192, TMPRSS2 rs12329760, TMPRSS2 rs2070788) and the presence of post-COVID symptoms in previously hospitalized COVID-19 survivors." (PMID 36360172, 2022). "A recent study confirmed that TMPRSS2 protease is related to the spread of COVID-19 and disease occurrence." (PMID 35745792, 2022). "The pharmacological inhibition of TMPRSS2 using serine protease inhibitors, such as camostat and nafamostat, has been proposed as a pharmacological treatment of COVID-19 patients." (PMID 35104687, 2022). "The TMPRSS2 gene is highly expressed in cancer tissues, specifically in PRAD tumors, implying susceptibility to SARS-CoV-2 and severity for COVID-19." (PMID 36364238, 2022). "In contrast, men have higher levels of angiotensin-converting enzyme 2 (ACE2), which is a well-known receptor of SARS-CoV-2, and the cellular serine protease TMPRSS2 which is necessary for COVID-19 entry into target cells." (PMID 36033355, 2022). "Targeting ACE2 and TMPRSS2 has therefore emerged as an important therapeutic strategy for the treatment of COVID-19 by preventing entry of SARS-CoV-2 into cells, thereby limiting viral replication." (PMID 35250984, 2022). "We then examined the relationship between TMPRSS2 and other targets for COVID-19 therapy, including ACE2, AXL, CTSL and FURIN." (PMID 35017320, 2022). "TMPRSS2-inhibitors are arguably better candidates for COVID-19 antivirals than those for ACE2 as knockout of TMPRSS2 protein causes no overt detrimental phenotype." (PMID 36560732, 2022). "Vitamin D with calcium metabolites provides immunological protection from COVID-19 viral activity and neutralize effects on TMPRSS2." (PMID 35517888, 2022). "This study revealed that rs12329760 in the TMPRSS2 gene, a missense variant common in East Asian populations, contributes to protection against SARS-CoV-2 infection and development of COVID-19." (PMID 36532428, 2022). "COVID-19 and the presence of virus can up-regulate TMPRSS2, facilitating the virus entry into syncytiotrophoblast and cytotrophoblast cells." (PMID 36177036, 2022). "SARS-CoV-2 tend to attack organs rich in ACE2 and TMPRSS2 because of their necessity for infection process of COVID-19." (PMID 35924838, 2022). "Our study further highlights TMPRSS2 as a promising target for antiviral intervention and opens the door for the usage of locally administered serpins as a treatment against COVID-19." (PMID 35532162, 2022).
COVID-19 (continued). "By analyzing the single-cell RNA-sequencing dataset (GSE171524) of COVID-19-infected lungs and control lungs, the expression levels of TMPRSS2 in COVID-19-infected lungs were significantly reduced compared to the control lungs." (PMID 36364238, 2022). "The serine protease inhibitor nafamostat has been proposed as a treatment for COVID-19, by inhibiting TMPRSS2-mediated viral cell entry." (PMID 34991643, 2022). "In the case of COVID-19, most genetic studies have focused on the role of the angiotensin-converting enzyme 2 (ACE2) and protease transmembrane protease serine 2 (TMPRSS2) polymorphisms." (PMID 35893072, 2022). "Another mechanism of SARS-CoV-2 entry is the transmembrane serine protease 2 (TMPRSS2) which is required for priming the SARS-CoV-2 viral protein S. This protein is important for the pathogenesis of COVID-19." (PMID 35812606, 2022). "We found that polymorphisms in TMPRSS2, ACE1, IFNAR2, and IFIH1 genes are associated with worse clinical outcomes (ICU admission) and increased mortality in patients with COVID-19, and this is influenced by sex and ethnicity." (PMID 36672770, 2022). "Future study on the link between the androgen and the sex difference in the Ace2/Adam17/Tmprss2 complex in COVID-19 and CKD is necessary." (PMID 35887687, 2022). "The current study investigates if patients with interstitial lung diseases (ILDs) such as IPF and LAM have elevated ACE2, TMPRSS2, and Furin levels, increasing their risk for SARS-CoV-2 infection and development of COVID-19." (PMID 35160229, 2022). "The patients with TMPRSS2 rs12329760 CC genotypes demonstrated significantly higher COVID-19 infection mortality than individuals with other genotypes; nevertheless, COVID-19-recovered patients had TT genotypes." (PMID 36457338, 2022). "COVID-19 is caused by the SARS-CoV-2 virus, which enters target cells via interactions with ACE2 and TMPRSS2." (PMID 35277472, 2022). "We proved that the proposed HPAEpiC culture strategy can provide a large-scale alveolar model expressing ACE2 and TMPRSS2 for COVID-19 research." (PMID 35046486, 2022). "The goal of this study was to gain a better insight into the expression of the SARS-CoV-2-related proteins ACE2, TMPRSS2, and FURIN in lung cancer cells, making them susceptible to SARS-CoV-2 infection and potentially affecting the course of COVID-19." (PMID 36077610, 2022). "To verify whether the TMPRSS2 rs2070788 polymorphism can predict the risk of death in older individuals with COVID-19 independent of other confounding factors, we performed a Cox’s proportional hazards regression model including potentially confounding factors associated with COVID-19 outcome." (PMID 36423166, 2022). "Understanding these interactions at the molecular level will be helpful to the development of therapeutics against SARS-CoV-2, which selectively inhibit TMPRSS2 and other serine proteases, in order to fight the COVID-19 threat." (PMID 35207518, 2022). "In this study, we used the crystal structure of TMPRSS2 as a virtual screening target to identify potentially effective drugs for COVID-19 treatment from the FDA database." (PMID 35807455, 2022). "Following the analysis of the large data collection, 20 curated genes were identified as biomarkers or therapeutic candidates for COVID-19 therapy, including TMPRSS2 and CXCL10." (PMID 36239108, 2022). "Several potential therapeutic targets associated with ECs for defeating COVID-19, including ACE2, transmembrane protease serine 2 (TMPRSS2), chemokine receptor 5 (CCR5), IL-8, CXCL-8 receptor (CXCR-2), nitric oxide (NO), and Neuropilin-1." (PMID 35741101, 2022). "Recently an in-depth genetic analysis of chromosome 21 using genome-wide association study data established that five polymorphisms within TMPRSS2 and near MXI gene were associated with a reduced risk of developing severe COVID-19." (PMID 36146782, 2022).
COVID-19 (continued). "Overall, 1,656 and 2,669 genes co-expressed with CXCL10 and TMPRSS2 respectively, were found to be common prostate cancer and COVID-19 progression." (PMID 36239108, 2022). "Regarding COVID-19 severity, the HLA-A*33, ACE1 Ins, and TMPRSS2 rs12329760T alleles were associated with protection against severe forms, while the HLA-B*38, HLA-C*6, and ApoE rs429358C alleles were associated with risk for severe forms of COVID-19." (PMID 35793369, 2022). "Recent studies have found that genetic components of the ACE2 and TMPRSS2 genes can mediate the effects on the severity of COVID-19." (PMID 35746659, 2022). "Pooled results demonstrated that polymorphisms in the ApoE, ACE1, TMPRSS2, CCR5, and HLA genes appear to be involved in the susceptibility to and/or severity of COVID-19." (PMID 35793369, 2022). "Consistent with the inhibitory role of RG4 in Tmprss2 translation and SARS-CoV-2 infection presented here, our results indicated that the protein level of TMPRSS2 was increased in the lungs of COVID-19 patients." (PMID 35301316, 2022). "Here, we aim to investigate the impact on COVID-19 of polymorphisms in ACE2 and TMPRSS2, serving as main SARS-CoV-2 cell entry gateways, as well as in Toll-like receptors (TLRs), acting as crucial actors of the immune system alert during infections." (PMID 35956081, 2022). "A study based on the understanding of the requirement of TMPRSS2 expression for viral entry in SARS-CoV-2 gave magnesium to patients for 12 weeks, which modified the TMPRSS2 phenotype, indicative of possible a role in intervention for COVID-19." (PMID 36423061, 2022). "To test this idea, we performed IHC staining to evaluate the expression of TMPRSS2 in human lung tissues from two healthy individuals and two patients who succumbed to COVID-19." (PMID 35301316, 2022). "By the time this review was prepared, the results of five clinical studies and several case reports investigating the therapeutic efficacy of TMPRSS2 inhibitors in COVID-19 patients were available." (PMID 35163273, 2022). "Angiotensin-converting enzyme-2 (ACE2) receptor plays a key role in the COVID-19 pathogenesis, while transmembrane protease, serine-2 (TMPRSS2) mediates priming of viral spike proteins with ACE2." (PMID 35730047, 2022). "Additionally, although the variation in ACE2 and TMPRSS2 expression may partially contribute to COVID-19 risk, many other risk factors for COVID-19 should also be considered, such as pre-existing medical conditions of cardiovascular diseases, diabetes, and chronic respiratory diseases." (PMID 34094637, 2021). "The host cell serine protease TMPRSS2 is an attractive therapeutic target for COVID-19 drug discovery." (PMID 34635581, 2021). "GSEA of the COVID-19 related gene sets revealed that both TMPRSS2 and CTSL belong to SARS top 50 geneshot AutoRIF along with SARS 133 Literature-Associated Genes from Geneshot GeneRIF." (PMID 34407143, 2021). "Further reports suggest that the nasal and bronchial airways expression of TMPRSS2 plays a role in the observed difference in COVID-19 severity between children and adults, particularly elderly adults and those with other comorbidities." (PMID 34072295, 2021). "Regarding COVID-19-associated target proteins, luteolin had the best binding activity with S-RBD and also showed promising affinities with Mpro, TMPRSS2, ACE2, CD147, and S-protein." (PMID 35069542, 2021). "One rationale for the increased COVID-19 risk in men is higher expression of androgen-driven ACE2 and/or TMPRSS2 expression." (PMID 33476304, 2021). "Numerous in silico studies were undertaken in the recent months after the emergence of COVID-19 to investigate new molecules, few of which are studying protease inhibitors for TMPRSS2." (PMID 34336361, 2021). "Here we performed a comprehensive analysis on NRP1 and TMPRSS2 in lung to provide information for treating comorbidity of COVID-19 with lung cancer." (PMID 34168096, 2021).
COVID-19 (continued). "Drugs based on the inhibition or blockage of TMPRSS2 protease are undergoing clinical trials as a therapeutic option for COVID-19 treatment." (PMID 34603376, 2021). "Our analysis suggests NRP1 as a potential therapeutic target, while sets an alert on targeting TMPRSS2 for treating comorbidity of COVID-19 and lung cancers." (PMID 34168096, 2021). "Here the expressions of ACE2 and TMPRSS2 in lung tissues from COVID-19 patients were used as positive controls, and sections incubated with rabbit IgG1 antibodies were used as isotype controls." (PMID 33995382, 2021). "Our data indicate a possible association between TMPRSS2 p.Val160Met polymorphism and SARS-CoV-2 infectivity and the outcome of COVID-19." (PMID 34001248, 2021). "Some symptoms in patients with COVID-19, such as cardiovascular, kidney, GI, and brain manifestations, are associated with the co-expression of ACE2 and TMPRSS2." (PMID 34768321, 2021). "The result of this study indicates that the severity of COVID-19 between adults and children, in part, can be attributed to the different expression levels of the TMPRSS2 and the ACE2 in airways tissues." (PMID 34527703, 2021). "Single-cell RNA sequencing revealed the expression of ACE2 and transmembrane serine protease 2 (TMPRSS2)—both known COVID-19 receptors—in podocytes and tubule epithelial cells, indicating the possibility for direct infection of the kidney by the virus." (PMID 34960687, 2021). "In view of these, ACE2, TMPRSS2, and Mpro have been considered as potential drug targets for COVID-19 therapy." (PMID 34647577, 2021). "Among them, TMPRSS2 has been shown to activate the spike-protein of COVID-19 for viral fusion and infectivity." (PMID 34068970, 2021). "Angiotensin-converting enzyme 2 (ACE2) and transmembrane protease serine 2 (TMPRSS2) are essentially involved in SARS-CoV-2 internalization into host cells playing a relevant role in the pathogenesis of COVID-19 in several species, including humans." (PMID 33765288, 2021). "(2020) observed that the expression of the TMPRSS2 gene is activated by IL-13, a highly expressed cytokine in COVID-19 and regarded as a predictive factor for mechanical ventilation independent of gender, age, and comorbidities." (PMID 34568081, 2021). "Several manifestations of COVID-19, such as cardiovascular, kidney and brain symptoms, are associated with expression of ACE-2 and TMPRSS2." (PMID 34399734, 2021). "Together, all of the data indicate a crucial involvement of the TMPRSS2 genetic variation, the p.Val160Met (rs12329760) in particular, in mediating the severity of COVID-19." (PMID 34001248, 2021). "This is the first study to demonstrate a possible association between TMPRSS2 p.Val160Met polymorphism and the degree of SARS-CoV-2 viral load as indicated by the Ct value of NAAT in patients with COVID-19." (PMID 34001248, 2021). "Repurposing of the mucolytic agent called bromhexine, a TMPRSS2 inhibitor, has been also proposed for COVID-19 therapy." (PMID 34222852, 2021). "The serine protease inhibitor camostat mesylate, approved in Japan to treat diseases, has been shown to block TMPRSS2 activity and is thus an interesting candidate to treat COVID-19 patients with pre-existing CAD." (PMID 33902676, 2021). "In a recent case-control study, it was shown that TMPRSS2 expression along with ACE2 in the nasopharyngeal area has a direct relation to necessity of oxygen supply in COVID-19 patients." (PMID 34336361, 2021). "We then studied the expression of ACE2 and TMPRSS2 across pooled healthy controls and the different types of COVID-19 patients." (PMID 34578338, 2021). "While we did not observe a significant association between genetically regulated expression of ACE2 and TMPRSS2 with COVID-19 hospitalization in our data, this difference can be explained by the different phenotypic definitions." (PMID 34315903, 2021).